MDM2 (MDM2 proto-oncogene)
Diseases named in the same sentence as MDM2 in open-access papers (continued):
Sharing a sentence is not in itself a finding about the gene and the disease.
tumor (continued). "In excised tumors, romidepsin reduced tumor weight (fold change compared to control: control 1.0 ± 0.2, romidepsin 0.48 ± 0.14; p = 0.04) and reduced MDM2 levels as measured by quantitative RT-PCR (fold change compared to control: control 1.0 ± 0.21, romidepsin 0.51 ± 0.07; p = 0.02)." (PMID 31620242, 2019). "Despite the ubiquitous accessibility of the MDM2 promoter, nearby distal regulatory elements of MDM2 were more accessible in uterine endometrioid cell lines, consistent with higher MDM2 gene expression observed in corresponding tumor samples from the TCGA cohort." (PMID 31554806, 2019). "This HDAC2 inhibition reduces MDM2 expression and abrogates tumor growth in vitro and in vivo." (PMID 31620242, 2019). "This study indicates that there may be a window for tumour-selective depletion of MDMX/MDM2 by spliceosome inhibition." (PMID 29796170, 2018). "The majority of tumor types had a small subset of patients with MDM2 amplification." (PMID 30148248, 2018). "Indeed, the EμEBNA1 transgenic tumour cell viability is dependent upon MDM2, demonstrated by MDM2 inhibition, suggesting a direct role for the activation of MDM2 in the EBNA1 mediated tumourigenic process." (PMID 29642420, 2018). "MDM-2 targeted siRNA along with pH-responsive di-block copolymer of poly (methacryloyloxy ethyl phosphorylcholine)-b-poly (diisopropanolamine ethyl methacrylate) PMPC-b-PDPA reduced 67% of tumor volume in NSLSC animal model." (PMID 29861465, 2018). "Mdm2 gene rs3730485 was also intimately related to tumour occurrence." (PMID 29892419, 2018).
tumor (continued). "Therefore, antagonizing MDM2 protein represents an attractive approach to combat tumor growth and expansion." (PMID 29748481, 2018). "Furthermore, the S-MDM2 transcript has a low expression in normal cells but is highly inducible and overexpressed in a number of tumors, whereas, the l-MDM2 transcript is constitutively expressed in both normal and tumor tissues." (PMID 29065514, 2017). "Similarly, MDM2-B (48 kDa), which is the most common MDM2 isoform observed in cancers, has exons 4–11 spliced out but is reported to promote tumor progression by inducing Cyclin D1 and Cyclin E in vivo." (PMID 29065514, 2017). "Conversely, RBM38 could also decrease the stability of p63, c-Myc and mouse double minute 2 homolog (MDM2) by bounding on their mRNA to inhibit tumor cells proliferation." (PMID 29052531, 2017). "Our goal was to determine whether combined MDM2 and PI3K/AKT/mTOR targeting is associated with higher anti-tumor activity than single agent alone in preclinical models of WDLPS/DDLPS." (PMID 28903316, 2017).
tumor (continued). "While, knocking down hnRNPA1 through the transfection of hnRNPA1 siRNA led to the increase of MDM2 at both protein level and gene level In vivo experiment, subcutaneous injection with estradiol every two days near the tumor at doses of 2.5mg/kg/d suppressed tumor growth and reduced MDM2 expression." (PMID 28035066, 2017). "Moreover, in a model of metastatic breast cancer, while MDM2 blockade potentiated the effects of carboplatin on inhibiting tumor growth, the therapy was well tolerated." (PMID 29065514, 2017). "Upon processing tumor tissues, we found that gossypol inhibited in vivo expression of MDM2." (PMID 28274247, 2017). "It will be interesting to test whether a more potent ALK inhibitor, such as PF06463922, in combination with CGM097 or other MDM2 antagonists can delay or prevent tumor regrowth after treatment termination." (PMID 28425916, 2017). "Moreover, Mdm2 promotes the stemness of murine induced pluripotent stem cells and human mesenchymal stem cells, and supports the survival of tumour cells." (PMID 27927750, 2017). "Since drug resistance to MDM2 inhibitors or current therapeutic agents can be acquired by tumor cells, pharmacological combination could be a successful strategy to improve the treatment outcome and to reduce the side-effects of the drugs." (PMID 28018226, 2016). "It is well known that accelerated tumor cell proliferation could occur as a result of CDKN2A/B deletion due to the direct removal of tumor suppressors and activation of tumor growth factors such as MDM2 and CDK4/6." (PMID 27090891, 2016).
tumor (continued). "However, the biological function of aberrantly spliced MDM2 isoforms varies from tumor promotion to growth arrest." (PMID 27129163, 2016). "Finally, we show that MDM2 suppresses the ability of NORE1A to induce senescence in a mutant Ras tumor cell line." (PMID 27023610, 2016). "Some pathways are stimulated in MDM2-positive tumours by decreased miRNA expression." (PMID 26918730, 2016). "Therefore, we assume that the inhibition of tumor growth in PC9-luc xenograft tumor was likely due to MDM2 knockdown induced apoptosis." (PMID 27259273, 2016). "The tumor growth was markedly inhibited in PC9 xenograft tumor model through inhibition of MDM2." (PMID 27259273, 2016). "The application of existing protocols to process microdissected formalin fixed clinical samples for proteomics screens 41 might define such tumor heterogeneity to impact on MDM2 drug biomarker discovery." (PMID 27273042, 2016). "To evaluate whether RNA editing may regulate MDM2, we first identified the microRNAs predicted to bind at RNA editing sites with significant editing level changes in at least one tumor type." (PMID 26980570, 2016). "Furthermore, the dendrimer/MDM2 siRNA polyplexes showed excellent activity in the inhibition of tumor growth in a PC9 xenograft tumor model." (PMID 27259273, 2016). "Moreover, MDM2 also acts as a tumor suppressor through the Akt pathway, inducing the ubiquitination and degradation of NFAT (an invasion-promoting factor), thereby blocking cancer cell motility and invasion." (PMID 27417709, 2016).
tumor (continued). "These tumours represent a rare subset which should be studied to establish whether other mechanisms such as MDM2 amplification can lead to an alternative pathway of HGSOC oncogenesis." (PMID 27840695, 2016). "Research shows that MDM2 may interfere with the tumor suppressor function of the transcription factor REST to inhibit p85 expression and thus to activate Akt phosphorylation." (PMID 27004407, 2016). "However, the TCGA data does not indicate a strong correlation between BCL11A and SIRT1 or MDM2 expression at least in the tumour context." (PMID 25574598, 2015). "With this hypothesis in mind, we mined the human tumor data generated by the TCGA Research Network and identified a rationally derived copy number cutoff for assignment of functionally relevant MDM2 amplification." (PMID 25730903, 2015). "This suggests that these derivative chromosomes are likely the result of a chromothriptic event in which a large fragment containing the MDM2 locus and the centromere is broken free from chromosome 12, later to be aggregated, either during tumor progression, or during cell culturing." (PMID 26328271, 2015). "p14ARF is a tumour suppressor and a negative regulator of MDM2." (PMID 25844600, 2015). "Furthermore, the reported overall amplification rate suffered from ascertainment bias, as a disproportionate number of the studies focused on tumor types previously reported to harbor high rates of MDM2 amplification." (PMID 25730903, 2015). "The overexpression of MDM2 is found in multiple tumor types (see reviews)." (PMID 26416444, 2015). "The expression of MDM2 protein in tumor tissue was downregulated by oroxylin A as well." (PMID 25902914, 2015). "This kinase, considered to act as a tumor suppressor by inhibiting tumor metabolism and associated cell growth signaling pathways has been described to suppress EMT by regulating the Akt-MDM2-Foxo3 signaling axis." (PMID 26451612, 2015). "MdmX and Mdm2 may work as partners and directly contribute to tumor formation, as observed by the immortalization and neoplastic transformation of retrovirus-mediated MdmX overexpression in primary mouse embryonic fibroblasts." (PMID 25973395, 2015). "In order to better understand which patients might realize the greatest benefit from MDM2 inhibitor treatment, we set out to identify the determinants of sensitivity and/or resistance by screening a broad panel of tumor cell lines." (PMID 25730903, 2015). "In certain tumours, MDM2 over-expression is due to an enrichment of the short form." (PMID 26589636, 2015).